GRIP1 (glutamate receptor interacting protein 1)
Description:
May play a role as a localized scaffold for the assembly of a multiprotein signaling complex and as mediator of the trafficking of its binding partners at specific subcellular location in neurons. Through complex formation with NSG1, GRIA2 and STX12 controls the intracellular fate of AMPAR and the endosomal sorting of the GRIA2 subunit toward recycling and membrane targeting (By similarity).
Synonyms: FRASRS3; GRIP
Tractability: Antibody: its Gene Ontology location is reachable by antibodies, with high confidence; UniProt places it where antibodies can reach, with medium confidence. PROTAC: its protein half-life has been measured.
Gene: Protein-coding gene on chromosome 12 (66,347,431 to 67,069,162, reverse strand). Ensembl gene ENSG00000155974.
Subcellular location: Cytoplasmic vesicle; Perikaryon; Cell projection, dendrite; Cytoplasm; Endomembrane system; Postsynaptic cell membrane; Postsynaptic density; Endoplasmic reticulum membrane
Pathways (Reactome):
Neuronal System: Trafficking of GluR2-containing AMPA receptors
Gene Ontology:
Molecular function: identical protein binding; protein binding; beta-catenin binding; signaling receptor complex adaptor activity
Biological process: intracellular signal transduction; neurotransmitter receptor transport, endosome to postsynaptic membrane; positive regulation of neuron projection arborization
Cellular component: cytoplasmic vesicle; endoplasmic reticulum membrane; cytoplasm; cytosol; endomembrane system; neuron projection; perikaryon; plasma membrane; postsynaptic density; postsynaptic membrane; dendrite
Genetic constraint (gnomAD): Loss-of-function variants: 30 observed, 98.11 expected, observed/expected ratio (o/e) 0.31, 90% interval 0.23 to 0.41. The upper end of that interval is the gene's LOEUF score, 0.41, which puts it in group 1 of 6, group 1 being the genes least tolerant of losing a copy. Missense variants: 956 observed, 1,194.6 expected, observed/expected ratio (o/e) 0.8, 90% interval 0.76 to 0.84. Synonymous variants: 445 observed, 454.39 expected, observed/expected ratio (o/e) 0.98, 90% interval 0.9 to 1.06.
Gene-disease validity (ClinGen):
ClinGen rates the evidence that GRIP1 causes each of these diseases.
Fraser syndrome 3 (autosomal recessive): Definitive.
Homologues: Orthologues: macaque GRIP1 (99% identical), chimpanzee GRIP1 (98% identical), rabbit GRIP1 (97% identical), guinea pig GRIP1 (96% identical), dog GRIP1 (95% identical), pig GRIP1 (95% identical), rat Grip1 (94% identical), mouse Grip1 (93% identical), tropical clawed frog grip1 (81% identical), zebrafish grip1 (76% identical), Caenorhabditis elegans magi-1 (13% identical), Drosophila melanogaster Magi (11% identical). Paralogues in human: GRIP2 (57% identical), MAGI1 (20% identical), MAGI3 (18% identical), MAGI2 (18% identical), SAV1 (5% identical), MAGIX (5% identical).
Diseases named in the same sentence as GRIP1 in open-access papers:
GRIP1 is named in the same sentence as 47 diseases in open-access papers, as found by Europe PMC text mining. Sharing a sentence is not in itself a finding about the gene and the disease. The quoted sentences say what the papers report.
Fraser syndrome (8 papers, 2013 to 2025). Fraser syndrome is a rare clinical entity including as main characteristics cryptophthalmos and syndactyly. "These include FRAS1, FREM1, and GRIP1, which are known to be associated with Fraser syndrome, suggesting a coordinated role in the biological processes underlying this disorder." (PMID 41426592, 2025). "In humans and mice, recessive loss-of-function mutations in FRAS1 and GRIP1 cause the rare, clinically overlapping congenital disorders Fraser Syndrome and Ablepharon Macrostomia Syndrome." (PMID 26110643, 2015). "Similar multi-organ defects have been reported in humans with GRIP1 mutations consistent with Fraser syndrome, a syndrome found with deletion of specific GRIP1 interacting proteins including Frem1 (Fras1 related extracellular matrix 1) and Fras1 (Fraser syndrome 1)." (PMID 27631377, 2016). "Recessive mutations in FRAS1, FREM2, and GRIP1 cause Fraser syndrome which is characterized by cognitive impairments, cryptophthalmos, syndactyly, genital and renal anomalies and a range of other structural defects including CDH, lung lobulation defects and anal anomalies (OMIM #219000)." (PMID 23536828, 2013). "Regarding the PPI network, FREM2 interacts with several proteins known to be associated with Fraser syndrome, such as FRAS1, FREM1, and GRIP1." (PMID 41426592, 2025). "Of the candidate genes, four genes (i.e., ITGA8, GRIP1, FREM1, and FREM2) were Fraser syndrome-related genes, encoding proteins that functionally converged on the glial cell-derived neurotrophic factor/RET/bone morphogenic protein (BMP) signaling pathways." (PMID 29197384, 2017). "Many of these genes seem to have unknown function in relation to cancer onset and progression but are known to play roles in other abnormalities (e.g., GRIP1 in Fraser Syndrome)." (PMID 31835892, 2019). "However, in one large literature review, abnormal lung lobulation was documented in 5/117 (4.3%) of cases of Fraser syndrome, which can be caused by recessive mutations in FRAS1, FREM2 and GRIP1." (PMID 23536828, 2013).
autism (4 papers, 2014 to 2023). Persistent deficits in social interaction and communication and interaction as well as a markedly restricted repertoire of activity and interest as well as repetitive patterns of behavior. "Interestingly, loss- or gain-of-function of GRIP proteins affects social interactions, and in humans, five missense GRIP1 variants leading to a gain-of-function have also been associated with autism." (PMID 30937469, 2019). "We also identified PSGs associated with communication disorders, such as autism (CNTNAP4, AHI1, FAN1, SNTG2, and GRIP1) and dyslexia (KIAA0319)." (PMID 33441416, 2021). "Several candidate autism susceptibility genes were hypermethylated (P <0.05) in the HMFA, including Shank3, Cacana1g, Gtf2i, Rapgef4, and Nbea in male offspring and Ext1, Ube3a, Erbb4, Grip1, Grm8, Reeln, Shank3, and Rbfox1 in female offspring." (PMID 24484737, 2014).
hyperglycaemia (3 papers, 2016 to 2021). "Obese mice with conditional macrophage-specific deletion of GRIP1 develop inflammation and substantial macrophage infiltration in metabolic tissues, fatty livers, hyperglycemia and insulin resistance; recapitulating metabolic disease through GRIP-1's glutamate receptor-independent actions." (PMID 32140136, 2020). "Moreover, obese mice conditionally lacking GRIP1 in macrophages develop massive macrophage infiltration and inflammation in metabolic tissues, fatty livers, hyperglycaemia and insulin resistance recapitulating metabolic disease." (PMID 27464507, 2016).
Insulin resistance (3 papers, 2016 to 2021). Increased resistance towards insulin, that is, diminished effectiveness of insulin in reducing blood glucose levels. "Because loss of GRIP1 impaired M(IL4) polarization and function in vitro, we evaluated the role of myeloid GRIP1 in the systemic metabolic homeostasis in a diet-induced obesity model of insulin resistance." (PMID 27464507, 2016).
autism spectrum disorder (2 papers, 2016 to 2021). A spectrum of developmental disorders that includes autism, and Asperger syndrome. "In previous studies, Grip1 knockout mice exhibited increased sociability and human GRIP1 gain of function mutations have been correlated with more severe social deficits in autism spectrum disorder." (PMID 33407853, 2021).
breast carcinoma (2 papers, 2017). "In addition, it has been reported that RhoGDI could stimulate the transcriptional activity of estrogen receptor α(ERα) via a RhoGTPase-dependent pathway that acts on estrogen receptor co-activators GRIP1 and CBP/p300 in breast cancer." (PMID 28060755, 2017).
lipoma (2 papers, 2015 to 2022). A benign, usually painless, well-circumscribed lipomatous tumor composed of adipose tissue. "In lipoma 5, exon 4 of HMGA2 was fused to a sequence 500 Mbp distal to HMGA2 in an intron of GRIP1 in 12q14.3." (PMID 26202160, 2015).
metabolic syndrome (2 papers, 2016 to 2021). A cluster of metabolic risk factors for CARDIOVASCULAR DISEASES and TYPE 2 DIABETES MELLITUS. "In vivo, GRIP1 deficiency in macrophages resulted in a metabolic syndrome-like disease when mice were challenged with HFD." (PMID 27464507, 2016).
Obesity (2 papers, 2016 to 2025). Accumulation of substantial excess body fat. "GRIP1 was evaluated over a decade ago in total body KO mice which were reportedly protected from HFD-induced obesity, displayed reduced FA uptake and increased lipolysis in WAT, as well as enhanced adaptive thermogenesis in BAT." (PMID 27464507, 2016).
schizophrenia (2 papers, 2012 to 2013). A major psychotic disorder characterized by abnormalities in the perception or expression of reality. "In neurons, BDNF-mediated mutual upregulation of GluR2 and GRIP1 can have considerable implications for the effects of the neurotrophin to offset schizophrenia and behavioral depression and promote memory maintenance and synaptic potentiation during late phase LTP (l-LTP)." (PMID 23460828, 2013). "However, AMPA receptor interacting proteins responsible for the trafficking of the receptors, SAP97 and GRIP1, are increased in schizophrenia." (PMID 22720072, 2012). "Additionally, SAP97 and GRIP1 were increased in schizophrenia, suggesting an increase in the rate of forward trafficking of AMPA receptors from the ER to the synapse." (PMID 22720072, 2012). "We have previously reported increased expression in DLPFC in schizophrenia of SAP97 and GRIP1, two proteins involved in the forward trafficking of AMPA receptors from the ER to the synapse." (PMID 22720072, 2012).
asthma (1 paper, 2021). "The present project confirms that the loss of GLCCI1 expression leads to GC insensitivity through downregulating the GR-GRIP1 pathway, which is associated with the increased interaction between IRF1 and GRIP1 and between IRF3 and GRIP1 in asthma." (PMID 34504850, 2021). "In short, global GLCCI1 knockout in Dex-treated asthmatic mice could reduce GR and GRIP1 expression, decreasing the less binding of GRIP1 to GR, which finally reduced Dex anti-inflammatory responses and led to GC insensitivity in asthma." (PMID 34504850, 2021). "This project determines the underlying mechanism that GLCCI1 deficiency attenuates GC sensitivity in dexamethasone (Dex)-treated Ovalbumin (OVA)-induced asthma mice and epithelial cells through upregulating binding of IRF1:GRIP1 and IRF3:GRIP1." (PMID 34504850, 2021).
cocaine addiction (1 paper, 2022). "Glutamate receptor-interacting protein 1 (GRIP1) is known to be associated with cocaine addiction, but the role of GRIP1 in D1-MSNs and D2-MSNs of the NAc in cocaine acquisition and reinstatement remains unknown." (PMID 36406750, 2022). "In cocaine addiction, GRIP1 knockout in the NAc enhances vulnerability to cocaine relapse, and calpain in the NAc core mediates the reconsolidation of drug reward memory through GRIP1 expression." (PMID 36406750, 2022). "Meanwhile, our behavioral data indicated that interference of the GRIP1-GluA2 interaction in D1-MSNs has a similar tendency to the results obtained when all types of neuronal targets are interfered by GRIP1-siRNA, which illustrates that GRIP1 in D1-MSNs plays a leading role in cocaine addiction." (PMID 36406750, 2022).
congenital diaphragmatic hernia (1 paper, 2013). A posterolateral defect of the diaphragm that allows passage of abdominal viscera into the thorax, leading to respiratory insufficiency and persistent pulmonary hypertension with high mortality. "Similarly, recessive mutations in Frem1 have been shown to cause congenital diaphragmatic hernia (CDH) which has not been documented in mice with Fras1, Frem2 or Grip1 mutations." (PMID 23536828, 2013).
dengue (1 paper, 2018). "The association of the four genes (CHST10, AHRR, PPP2R5E and GRIP1) from the xenobiotic metabolism signaling pathway with Thai DF patients is the first genetic evidence for its implication in dengue pathogenesis, although functional studies have already indicated this association before." (PMID 29447178, 2018). "For dengue fever (DF), we found evidence of significant association with CHST10, AHRR, PPP2R5E and GRIP1 genes, which participate in the xenobiotic metabolism signaling pathway." (PMID 29447178, 2018).
Glucose intolerance (1 paper, 2016). Glucose intolerance (GI) can be defined as dysglycemia that comprises both prediabetes and diabetes. "We predict that in a time-frame of longer than 20 weeks of HFD used in this study, WT mice will ultimately succumb to glucose intolerance and steatotic liver, however, the absence of GRIP1 in myeloid cells dramatically accelerates this process." (PMID 27464507, 2016).
Hyperinsulinemia (1 paper, 2016). An increased concentration of insulin in the blood. "There was no detectable difference in Akt phosphorylation between genotypes in control (PBS-injected) mice despite baseline hyperinsulinemia of GRIP1 cKO, and insulin-injected WT mice displayed a significantly higher level of pAkt in eWAT and muscle." (PMID 27464507, 2016). "Thus, the lack of GRIP1 in macrophages sensitizes mice to metabolic challenge resulting in chronic inflammation of metabolic tissues, hyperinsulinemia and glucose intolerance under HFD conditions." (PMID 27464507, 2016).
liver cancer (1 paper, 2017). An epithelial or non-epithelial malignant neoplasm that arises from the liver. "Here, we found that an orphan nuclear NR2E3 maintains AHR expression, and forms an active transcriptional complex with transcription factor Sp1 and coactivator GRIP1 in MCF-7 human breast and HepG2 liver cancer cell lines." (PMID 28878246, 2017).
renal agenesis (1 paper, 2013). Renal agenesis (RA) is a form of renal tract malformation characterized by the complete absence of development of one or both kidneys (unilateral RA or bilateral RA respectively), accompanied by absent ureter(s). "Apoptosis of cells in the metanephric mesenchyme, leading to renal agenesis, is also seen in mice that lack the cytosolic adapter protein GRIP1, which plays a critical role in trafficking FRAS1 and FREM2 to the plasma membrane." (PMID 23536828, 2013). "Given the known interactions between these proteins, it is not surprising that FREM1-, FRAS1-, FREM2- and GRIP1-deficient mice have overlapping patterns of defects that include cryptophthalmos and syndactyly–which are likely to be secondary effects of blister formation–and renal agenesis." (PMID 23536828, 2013).
thrombosis (1 paper, 2016). "Because platelet activation was normal in GRIP1-/- platelets, but mice had a thrombosis defect, we next sought to determine whether GRIP1-/- platelets have altered adhesion to stimulated endothelial cells using an in vivo platelet rolling assay." (PMID 27631377, 2016).
tumor (6 papers, 2013 to 2025). "The top upregulated ‘green’ module gene in macrophages from the tumor was Glutamate receptor-interacting protein 1 (GRIP1), which was linked to the regulation of T cell activation in a previous study." (PMID 33918618, 2021).
cancer (2 papers, 2014 to 2019). A tumor composed of atypical neoplastic, often pleomorphic cells that invade other tissues. "The expression of SRC-1 and GRIP-1 increases in cancer and recurrent PCa after medical or surgical castration, suggesting that GRIP-1 and SRC-1 may be involved in the development and progression of PCa." (PMID 24699278, 2014).
metabolic disease (2 papers, 2016 to 2020). A congenital disorder (due to inherited enzyme abnormality) or acquired (due to failure of a metabolically important organ) disorder resulting from an abnormal metabolic process. "Thus, coregulators such as GPS2, GRIP-1, NCoRs, and HDAC3 are critical regulators of macrophage reprogramming in metabolic disease." (PMID 32140136, 2020).
GRIP1 also shares sentences with these, for which no sentence is quoted: ablepharon macrostomia syndrome (1 paper); communication disorder (1); connective tissue disorder (1); dyslexia (1); dysplasia (1); epilepsy (1); frontotemporal lobar degeneration (1); glioblastoma (1); heart malformations (1); Hepatic steatosis (1); Hyperkalemia (1); Hypertension (1); Hypokalemia (1); infection (1); kidney damage (1); lung carcinoma (1); melanoma (1); multiple sclerosis (1); neurological disorders (1); osteogenesis imperfecta (1); osteosarcoma (1); prostate carcinoma (1); sarcopenia (1); Sepsis (1); steatosis (1).